TLR4 (toll like receptor 4)
Diseases named in the same sentence as TLR4 in open-access papers (continued):
Sharing a sentence is not in itself a finding about the gene and the disease.
liver fibrosis (continued). "Previous data showed that the blockade of TLR4 signaling or the use of antibiotics that reduce the microbiota improves experimental liver fibrosis." (PMID 36430244, 2022). "Oral IAP can protect the intestinal barrier and further prevent the development of liver fibrosis through a TLR4-mediated mechanism." (PMID 35563935, 2022). "We have reported that the COX-2/PGE2 axis was involved in the formation of liver fibrosis induced by Sj infection under the control of the TLR4 pathway." (PMID 35461268, 2022). "The enhanced mRNA level of LPL in hepatic stellate cells increases the uptake of cholesterol from serum lipoproteins, which induces an increase in TLR4 signaling and the exacerbation of liver fibrosis." (PMID 35369079, 2022). "TLR4 pathway activation has been reported to be involved in mice liver fibrosis induced by hepatitis virus infection, alcohol abuse, biliary ligation, carbon tetrachloride 4 treatment, and Schistosoma japonicum (Sj) infection." (PMID 34034779, 2021). "A cumulative action of LPS and these endogenous substances results in the TLR4 mediated HSCs activation, which finally culminates in liver fibrosis." (PMID 33336563, 2021). "As shown in the previous study, the TLR4 down‐regulation in the TLR4 knockout mice alleviated liver fibrosis in the experimental liver injury model." (PMID 33336563, 2021). "This study also demonstrates that the TLR4 shRNA encapsulated within VitA‐coupled liposomes can be a potential therapeutic agent for liver fibrosis treatment." (PMID 33336563, 2021). "LPS induces liver fibrosis by translocating across the gut barrier, into the portal vein, where it then enters the liver, and activates the TLR4 pathway resulting in a variety of downstream signaling that lead to fibrosis." (PMID 33391458, 2021). "The outcome of this study suggests that the TLR4‐mediated signalling pathways activation in HSCs plays a crucial role in the fibrogenesis and inflammation in liver fibrosis." (PMID 33336563, 2021). "An imbalanced intestinal microecology can activate the lipopolysaccharide/Toll-like receptor-4 (LPS-TLR4) signaling pathway, increase the intestinal wall permeability, cause mesenteric epithelial cells to develop ischemic necrosis, and induce liver fibrosis." (PMID 34367091, 2021). "NS398 was an effective inhibitor of this axis to ameliorate liver fibrosis induced by TLR4 pathway activation and Sj infection." (PMID 34034779, 2021). "A crucial role of TLR4 in fibrogenesis was highlighted in experiment where TLR4 mutant mice showed decreased liver fibrosis in response to toxic agents." (PMID 34045968, 2021). "A previous study indicated that Oxymatrine alleviated CCl4-induced liver fibrosis by inhibiting TLR4 and TGF-β1 signaling pathways." (PMID 34422075, 2021). "The effects of eritoran were mediated by the successful suppression of the hepatic TLR4 downstream pathway and blocking of LPS-TLR4 signaling in HSCs and KCs and were examined in two liver fibrosis mouse models." (PMID 34205789, 2021). "The liver's ability to detoxify bacterial LPS is hampered in advanced stages of liver fibrosis; however, the exogenous intestinal bacterial LPS induces the TLR4 activation." (PMID 33336563, 2021). "The study also demonstrated that AR was potent for downregulating the expression of HMGB1/RAGE/cJun pathway and HMGB1/TLR4/NF-κB pathway, thus protecting rats against CCl4-induced liver fibrosis." (PMID 33790974, 2021). "We have shown that the positive feedback regulation between transglutaminase 2 (TGM2) and TLR4 signaling in HSCs correlated with liver fibrosis after Sj infection." (PMID 34034779, 2021). "Sophocarpine, a matrine-type alkaloid reported from Sophora tonkinensis, reduced total bilirubin (TBIL) and aminotransferase serum levels and alleviated liver fibrosis by inhibiting the toll-like receptor-4 (TLR4) pathway." (PMID 33503905, 2021). "Thus, HSCs associated with TLR4 might be an ideal therapeutic target for liver fibrosis." (PMID 33336563, 2021).
liver fibrosis (continued). "Toll-like receptor-4 (TLR4) mutation and gut sterilization prevent hepatic fibrosis in mice, revealing that gut-derived LPS contribute to hepatic fibrosis." (PMID 34956204, 2021). "Secondly, thrombin was reported as a critical mediator in LPS-induced liver damage and gut-derived-LPS through TLR4 activation was significantly involved in CCl4-induced liver fibrosis." (PMID 34045968, 2021). "Our studies showed the inhibitory effects of PNS on TLR4-mediated inflammation, which improved hepatic fibrosis in DIO mice." (PMID 33656663, 2021). "We have also explored the effect of the TLR4 gene‐specific shRNA as a therapeutic agent in carbon tetrachloride (CCl4) induced liver fibrosis in mice." (PMID 33336563, 2021). "Literature research found that HMGB1, a cytokine abundantly enriched in patients with liver fibrosis, mediated TLR4//NF-κB signaling pathway is one of the important pathways for liver aseptic inflammation." (PMID 33790974, 2021). "Especially, TLR4-MyD88 pathway promoted liver fibrosis in a mouse BDL model by enhancing TGF-β signaling." (PMID 34830293, 2021). "LPS is a representative Toll-like receptor 4 (TLR4) agonist and can induce MSCs to exert an immunosuppressive phenotype, necessary in order to reduce liver fibrosis-related inflammation." (PMID 34948088, 2021). "TLR4 KO mice have been shown to develop an attenuated degree of liver fibrosis in CBDL and CCl4 models compared to WT mice." (PMID 33391458, 2021). "This indicated that liver fibrosis was induced by Sj infection through the activation of TLR4 signaling and then the COX2/PGE2 axis." (PMID 34034779, 2021). "The result of this demethylation is increased TLR4 transcription and activation of the TLR4/MyD88/NF-kB signaling pathway, which has a well-established role in liver fibrosis." (PMID 33791228, 2021). "Oral IAP protects the gut barrier and further prevents the development of liver fibrosis via a TLR4-mediated mechanism." (PMID 33391458, 2021). "While it is known that LPS is a substrate for IAP, and that IAP decreases luminal LPS 6, we asked the question if the ability of IAP to prevent liver fibrosis is dependent on the TLR4 pathway." (PMID 33391458, 2021). "In this study, we investigated the relationship between the COX2/PGE2 axis and TLR4 signaling in the induction of liver fibrosis in mice during Sj infection and in vitro cultured HSCs." (PMID 34034779, 2021). "The current study established, for the first time to our knowledge, the potential crosstalk between TF, PAR1 and TLR4 in liver fibrosis." (PMID 34045968, 2021). "The molecular link between liver fibrosis and inflammation was shown to be TLR4 signaling, which promotes HSC activation and modulates TGF-β1 signaling." (PMID 32296336, 2020). "Lipopolysaccharides (LPS) trigger toll-like receptor 4 (TLR4) expressed by Kupffer and hepatic stellate cells to activate transforming growth factor β signaling that leads to the development of hepatic fibrosis and eventually cirrhosis." (PMID 32824268, 2020). "In particular, lipopolysaccharide (LPS), a cell wall component of intestinal gram-negative bacteria, is a canonical ligand for Toll-like receptor 4 (TLR4) signaling in promotion of liver fibrosis." (PMID 32575352, 2020). "For example, MicroRNA-326, a small and endogenous noncoding RNA, was found to attenuate the hepatic stellate cell activation and the liver fibrosis by inhibition of TLR4 signaling pathway." (PMID 32425800, 2020). "Several lines of evidence indicate the role of Toll-like receptor 4 (TLR4) in the pathogenesis of liver fibrosis or NASH in mice." (PMID 31969650, 2020). "Recently, it has been reported that the TLR4-mediated NF-κB signaling pathway which can cross-talk with the TGF-β/samds signaling pathway plays a very important role in the pathogenesis of hepatic fibrosis and cholestatic injuries." (PMID 33469517, 2020).
liver fibrosis (continued). "In HSCs, TLR4-mediated hepatic fibrosis appears to depend on transforming growth factor-β (TGF-β)-dependent collagen production." (PMID 32283542, 2020). "LPS/TLR4 pathway in HSCs is related to the development of liver fibrosis, which regulates the expression of pro-inflammatory cytokines and controls cell survival." (PMID 33290258, 2020). "Particularly, dietary flavonoids, potential therapeutic agents in the therapy of liver fibrosis, have been proved to possess the ability to inhibit inflammation by modulating intracellular NF-κB signaling through TLR4." (PMID 32425800, 2020). "Collectively, the results of our study demonstrate aspirin suppresses hepatic fibrosis by exerting various anti-inflammatory effect that inhibit signaling in the TLR4 pathway, which in turn leads to inhibition of HSC activation and proliferation." (PMID 32283542, 2020). "Hypoxia has been recognized as an inducer of the activation of the TLR4/MyD88/NF-κB pathway in hepatic ischemia/reperfusion injury and liver fibrosis." (PMID 33195243, 2020). "The interaction of HMGB1 to TLR4 activates an inflammatory response and has been indicated to participate in liver fibrosis." (PMID 32425800, 2020). "Another group of Egyptian investigators demonstrated links between the TLR4 expression and liver fibrosis in chronic HCV patients." (PMID 32944845, 2020). "LPS-mediated TLR4 activation and NF-κB inflammatory signaling are believed to play an essential role during the development of the liver fibrosis." (PMID 31533364, 2019). "The positive feedback regulation between tTG and Toll-Like Receptor 4 signaling in hepatic stellate cells correlates with liver fibrosis resulting from Sj infection." (PMID 31200771, 2019). "TLR4-mutant mice, which lack responsiveness to LPS, are resistant to liver fibrosis, cirrhosis, and HCC." (PMID 30990169, 2019). "In conclusion, our current study demonstrated that Andro ameliorated liver fibrosis in part through suppressing the activation of the TLR4/NF-κB and TGF-β1/Smad2 signaling pathways." (PMID 29743985, 2018). "Given that TLR4 enhances TGF-β1 signaling in hepatic fibrosis and Andro downregulates the expression of TGF-β1, we suppose that the protection of Andro against liver fibrosis has a direct correlation with shutting down the TLR4 and TGF-β1 signaling pathways." (PMID 29743985, 2018). "TLR4 plays a vital role in the inflammatory response during liver fibrosis, which can upregulate the profibrogenic and proinflammatory cytokines through the activation of NF-κB." (PMID 29743985, 2018). "Endotoxin, a ligand for TLR4, activates chronic liver function damage, hepatitis, and liver fibrosis through activation of the TLR4 signaling pathway, ultimately promoting the development and progression of HCC." (PMID 30104473, 2018). "In contrast to IL-10, the signaling of LPS/TLR4 in hepatic stellate cells plays a crucial role in the progression of liver fibrosis by inducing the expression of cytokines/chemokines that recruit KC cells, which secrete the profibrogenic cytokine TGF-β." (PMID 30022981, 2018). "Many acute and chronic liver diseases of various etiologies are accompanied or even mainly driven by an inflammatory reaction initiated by KC via the activation of the TLR4 pathway leading to parenchymal damage, liver fibrosis, and eventually to liver failure." (PMID 29795632, 2018). "It has been suggested, that TLR4 enhances hepatic fibrosis through several mechanisms and that TLR4 plays distinct roles in the pathogenesis of renal fibrosis." (PMID 30102719, 2018). "As an essential cell surface protein for LPS recognition, TLR4 can activate HSCs and promote liver fibrosis." (PMID 28423574, 2017). "Results showed that the level of FN was correlated with the level of TGM2, TLR4, and the extent of liver fibrosis during Sj infection." (PMID 29321784, 2017).
liver fibrosis (continued). "Recently, it has been demonstrated that TLR4 involves in the pathogenesis of fibrosis including hepatic fibrosis and TLR4 is a key regulator of HSC activation." (PMID 28634394, 2017). "TLR4 activation leads to boosting of TGF- signaling with subsequent hepatic fibrosis through down-regulation of the transforming growth factor (TGF)-beta." (PMID 29379592, 2017). "We performed real-time PCR and Western blot analyses to determine differential expression of molecules known to be involved in TLR4 signaling pathway and the biomarkers of hepatic fibrosis, respectively." (PMID 28634394, 2017). "In this work, we found that TLR4 pathway activation correlated with the severity of liver fibrosis post Sj infection." (PMID 29321784, 2017). "TGM2 and TLR4 levels display a similar pattern of expression changes that correlates with the extent of liver fibrosis post Sj infection." (PMID 29321784, 2017). "TLR4 plays a key role in the development of liver fibrosis; lipopolysaccharide (LPS) ligand from the gut microbiota activates TLR4 on HSCs, influencing downstream signalling and resulting in myofibroblast proliferation and ECM production." (PMID 28761060, 2017). "The TLR4-triggered MyD88 pathway was found to be crucial to hepatic fibrosis by potentiating pro-fibrotic TGF-β1 signalling." (PMID 29247242, 2017). "Studies suggested a critical role of LPS/TLR-4 signaling axis in the inflammatory pathways associated with NASH36, and the Inhibition of LPS-TLR4 signaling with antibiotics attenuated liver fibrosis development in rat NASH model." (PMID 28051126, 2017). "This early protective function of TLR4 renders the use of Tlr4 (−/−) mice unsuitable for the study of liver fibrosis at the late stage of Sj infection." (PMID 29321784, 2017). "TLR4 signaling can be activated in the HSCs of mice with liver fibrosis induced by biliary ligation." (PMID 29321784, 2017). "First, TLR4 plays a pivotal role in the pro-inflammatory response and liver fibrosis, the downregulation of TLR4 signaling pathway following decreased endotoxin after FMT would lead to the inhibition of TGF-β1 and α-SMA expression." (PMID 28484247, 2017). "This novel connection between TGM2 and TLR4 pathway activation in liver fibrosis induced by Sj infection enhances our understanding of liver diseases." (PMID 29321784, 2017). "Collectively, these results establish a novel positive feedback regulation in which Sj infection activated TLR4 signal pathway increases the expression of TGM2, which in turn contributes to HSCs activation through TLR4 pathway and then causes liver fibrosis." (PMID 29321784, 2017). "Recent studies show that TLR4 plays an important role in several other types of liver fibrosis, but the mechanism of TLR4 in PABF is yet really unclear." (PMID 28634394, 2017). "The aim of this work is to examine the expression of TLR4 in HCV-infected patients with different stages of fibrosis to identify the potential role of TLR4 in the induction of liver fibrosis." (PMID 29379592, 2017). "The results revealed that liver fibrosis progression has a positive correlation with age, TLR4 expression, viral load, ALT, AST, total bilirubin and PT, and negative correlation with platelet count and serum albumin." (PMID 29379592, 2017). "Following BDL, TLR4-deficient mice exhibits significantly reduced inflammation and hepatic fibrosis, indicating that TLR4 is essential in liver fibrosis." (PMID 29403377, 2017). "In general, the positive feedback regulation between TGM2 and TLR4 signaling in HSCs correlated with liver fibrosis post Sj infection." (PMID 29321784, 2017). "In this study, we aimed to set up a preferable pathophysiological situation, which allows us to better assess the role of TLR4 in hepatic fibrosis and pre-cancerogenous liver injury." (PMID 27391331, 2016).
liver fibrosis (continued). "The effect of TLR4 on the development of hepatic fibrosis has so far been investigated in artificial models only with fibrosis induced by chemicals (CCl4, TAA) or surgery (BDL)." (PMID 27391331, 2016). "The overall anti-pro-inflammatory and anti-fibrotic effects of miR-146a-5p involved in the LPS/TLR4 mediated hepatic fibrosis need to be further investigated in the animal model in the future study." (PMID 27399683, 2016). "In the present study, we combined the two genetic mouse models to establish a novel preclinical model for the analysis of TLR4 effects on liver fibrosis." (PMID 27391331, 2016). "Lipopolysaccharide (LPS)/toll-like receptor 4 (TLR4) signaling pathway is demonstrated to be involved in the hepatic fibrosis." (PMID 27399683, 2016). "The results of clinical and experimental studies suggest that endotoxin/toll-like receptor 4 (TLR4)-mediated proinflammatory and profibrotic signaling activation is critical in the development of hepatic fibrosis." (PMID 26785354, 2016). "The fundamental role of TLR4 activation in the development of hepatic fibrosis has been shown by using TLR4 mutant mice as well as antibiotic treatment." (PMID 26785354, 2016). "Toll-like receptors, especially TLR2 and TLR4, are central mediators of the inflammation during liver fibrosis." (PMID 25954568, 2015). "TLR4 is a member of the TLRs family and a receptor for LPS, has been found to be closely related to liver fibrosis." (PMID 26083117, 2015). "Almost all hepatic cells with elevated levels of TLR4 are related to fibrotic progression and promote liver fibrosis." (PMID 25897319, 2015). "In consequence, HMGB1-TLR2/TLR4-NF-κB signaling pathway appears as a potential therapeutic target to suppress inflammation in liver fibrosis." (PMID 25954568, 2015). "Several lines of evidence indicated that LPS/TLR4 signaling provides a mechanistic link between inflammation and fibrosis, and plays an important role in liver fibrosis." (PMID 26222337, 2015). "The inhibition of TLR4 has been reported to antagonize AngII-induced cardiac fibrosis, the activity of TLR4 in hepatic stellate cells enhances liver fibrosis, and the activity of TLR4 in skin fibroblasts enhances SSc." (PMID 24904424, 2014). "In other murine models of hepatic fibrosis, increased level of LPS in the portal circulation induce activation of NF-κB in HSCs by binding to TLR4, the expression of which is also up-regulated in this process." (PMID 25116007, 2014). "TLR4 is expressed on both parenchymal and non-parenchymal cells in the liver, and several animal studies support the contribution of TLR4 in the development of liver fibrosis." (PMID 24904576, 2014). "A recent report demonstrated that LSECs mediate angiogenesis and subsequent liver fibrosis via TLR4 signaling." (PMID 24904576, 2014). "Mice deficient for TLR4, CD14, MyD88, or TRIF exhibit reduced liver fibrosis in experimental fibrosis models." (PMID 24904576, 2014). "LPS regulated TGFβ1-induced signals from HSC in TLR4/MyD88 in a dependent manner, thus modulating liver fibrosis in NASH." (PMID 23441159, 2013). "More recent studies have demonstrated key roles for other pathways, including TLR4 and Jak/Stat3 in hepatic fibrosis." (PMID 22973518, 2012). "Mice with deficiencies in components of TLR4 signaling pathway, CD14, LPS binding protein (LBP), or TLR4 have impaired TLR signaling and are less susceptible to liver fibrosis." (PMID 22973518, 2012). "A comparable significance of TLR4 for liver fibrogenesis has been noted in cholestatic or toxic liver fibrosis in mice." (PMID 23087650, 2012). "Recent studies suggest that TLR-4 participates in the production of hepatic fibrosis by activation of HSCs by TGF-β." (PMID 22114589, 2011). "In this study, the mice with TLR4-mutant endogenous liver cells exhibited a significant reduction of liver fibrosis, and the mice with TLR4-wild endogenous liver cells had a sufficient degree of fibrosis in the liver after BDL." (PMID 20706677, 2010).